STAT3 (signal transducer and activator of transcription 3)
Diseases named in the same sentence as STAT3 in open-access papers (continued):
Sharing a sentence is not in itself a finding about the gene and the disease.
gastric cancer (continued). "The results of this study showed that lncRNA RPSAP52 was elevated dramatically in gastric cancer cells and lncRNA RPSAP52 depletion was found to exert anticancer effects in gastric cancer via regulating miR-665/STAT3." (PMID 35322746, 2022). "Our data revealed decreased phosphorylation of PTK2, c-JUN, and STAT3 upon inhibition and siRNA-mediated silencing of CAMKK2 in gastric cancer cells." (PMID 35646067, 2022). "Our results also disclose that there is a negative correlation between palmitic acid and LAMC1 with miR-193a-3p in gastric cancer cells and LAMC1 is the target of miR-193a-3p regulated by p-STAT3." (PMID 35541892, 2022). "The correlation results of STAT3 and HEIH expression in gastric cancer tissue showed that STAT3 and HEIH showed coexpression positive correlation." (PMID 36246567, 2022). "Our western blot data revealed decreased phosphorylation of PTK2 at Y925, p-c-JUN at S73, STAT3 at Y705, and AMPK at T172 upon both inhibition and silencing of CAMKK2 in gastric cancer." (PMID 35646067, 2022). "In conclusion, the results above revealed that terphenyllin blocked the STAT3 signaling pathway in both MKN1 and BGC823 gastric cancer cell lines." (PMID 35401187, 2022). "In this study, when EMT induced by PlexinA1/β2-AR promoted the migration of gastric cancer cells, the JAK/STAT3 pathway was activated, and AG490 and Stattic reversed these effects." (PMID 35517411, 2022). "GC-MSCs inhibit the chemotaxis, survival, activation, and function of neutrophils through the IL-6/STAT3/ERK1/2 signaling pathway and promote the development of gastric cancer." (PMID 36439438, 2022). "It has been shown to induce autophagy and apoptosis in gastric cancer cells by activating mitochondrial ROS accumulation and silencing the JAK2/STAT3 pathway." (PMID 35559037, 2022). "In the current study, by DNA methylation microarray, we further identified a potential STAT3 target, C11orf87, showing hypomethylation in AGS gastric cancer cells depleted with STAT3 and patients with lower STAT3 activation." (PMID 33886682, 2021). "Tissue microarray also showed a positive trend between STAT3 and YWHAZ expression in gastric cancer patients (n = 60)." (PMID 33718136, 2021). "In this study, by using DNA methylation microarray, we identified a potential STAT3 target, C11orf87, showing promoter hypomethylation in gastric cancer patients with lower STAT3 activation and AGS gastric cancer cell lines depleted with STAT3 activation." (PMID 33886682, 2021). "TQ inhibited STAT3 phosphorylation at Tyr705 due to JAK2 and Src activity suppression in gastric cancer cell line (HGC27) investigations." (PMID 35010954, 2021). "In gastric cancer, OSM–OSMR can promote the proliferation, migration, invasion, and metastasis of tumor cells through the activation of STAT3/FAK/Src signals." (PMID 34422217, 2021). "CCL20/CCR6 induced gastric cancer EMT through the activation of the AKT pathway in response to CrkL; similar results were found with CCL21/CCR7 axis activated JAK2/STAT3 signaling pathways in promoting stemness of OSCC EMT progression." (PMID 34943853, 2021). "The result was in agreement with previous reports showing that EGCG treatment results in a drastic decrease in STAT3 activity in gastric cancer; EGCG suppressed the phosphorylation of STAT3 in neck squamous-cell carcinoma." (PMID 33747527, 2021). "As compared with parental cells, depletion of STAT3 resulted in demethylation of a putative STAT3 target, miR-193a, in AGS gastric cancer cells." (PMID 33718136, 2021). "Recent studies have shown that HCC and gastric cancer-derived GM-CSF bind neutrophil receptors and stimulate JAK2 and STAT3 phosphorylation that promotes expression of PD-L1 on the neutrophil surface, which binds and inhibits PD-1 on cytotoxic T cells." (PMID 33406733, 2021).
gastric cancer (continued). "Interestingly, one recent study reported that SHOX2 was among the most up-regulated genes following the induction of STAT3 activation in Helicobacter pylori-infected patients with gastric cancer, which suggests that SHOX2 may contribute to the initiation and progression of gastric carcinogenesis." (PMID 34465361, 2021). "Bisulfite pyrosequencing and tissue microarray were performed to investigate the promoter methylation of miR-193a and expression of STAT3, YWHAZ in patients with gastritis (n = 8) and gastric cancer (n = 71)." (PMID 33718136, 2021). "The results showed that the expressions of STAT3 and SLCO4A1-AS1 were positively correlated in gastric cancer tissues (r = 0.142, P < 0.05), but STAT3 was negatively correlated with miR-149-5p (r = -0.622, P < 0.001)." (PMID 34712324, 2021). "The phosphorylation of JAK kinase can lead to STAT3 and STAT5 activation in diverse tumor cell lines, including gastric carcinoma cells." (PMID 33807326, 2021). "In gastric carcinoma, cancer cell–secreted TGF-β1 interacted with IL-6, thus inducing STAT3 activation and promoting the extensive metastasis of cancer cells." (PMID 34867344, 2021). "Hence, these results suggested that STAT3 might regulate lipid homeostasis in stomach cancer." (PMID 32486001, 2020). "For example, STAT3-induced the transcriptional activation of lncRNA lncRNA HAGLROS and strengthens the oncogenic potential of HAGLROS in gastric cancer." (PMID 32694944, 2020). "In human gastric cancer cells (AGS) EGCG >10 μM reduce dose-dependently VEGF expression and secretion mediated by signal transducer and activator of transcription 3 (Stat3) activity." (PMID 31979082, 2020). "STAT3 promotes the increased expression of lncRNA HAGLROS, which leads to further progress of gastric cancer." (PMID 32831016, 2020). "In gastric cancer, IGF1/IGF1R/STAT3 signaling‐inducible IFITM2 promotes gastric cancer growth and metastasis." (PMID 32851683, 2020). "Treatment with the inhibitors of STAT3 and NFAT pathway, however, significantly reduced xenograft tumor sizes and retarded growth rates of NOC-transformed cells and gastric cancer cells." (PMID 32041943, 2020). "In the present review, we focus on the role and regulation of STAT3 in gastric cancer (GC)." (PMID 32545648, 2020). "Similar observations were made in gastric cancer where CAF-secreted IL-6 induced EMT and metastasis through STAT-3 pathway activation." (PMID 33553157, 2020). "In addition, PD-L1 overexpression could restore the miR-502-5p-overexpression induced cellular effects whereas CD40/STAT3 overexpression could partially restore the miR-502-5p-overexpression suppressed gastric cancer cells proliferation, migration and invasion." (PMID 32821248, 2020). "In cases of gastric cancer, CAFs promote EMT incells by secreting enough IL-6 that in turns activates the STAT-3 pathway." (PMID 32167126, 2020). "STAT3 signaling drives transcription activation of EZH2 and mediates poor prognosis in gastric cancer." (PMID 32831016, 2020). "Collectively, these results support a notion that STAT3/MSK1/NFATc2 form a functional axis in carcinogen-induced gastric tumor development, and provide potential therapeutic targets for human gastric cancer." (PMID 32041943, 2020). "We found that CARD had inhibited the levels of phosphorylated STAT3 in AGS cells, which suggested that CARD prevents gastric cancer development through down-regulating the activation of STAT3 in AGS cells." (PMID 31028131, 2019). "In the present study, we highlight the unique ability of stromal GC-MSCs to induce the polarization of macrophages into a pro-tumor M2 subtype within the gastric cancer niche through the secretion of IL-6 and IL-8 via the JAK2/STAT3 signaling pathway." (PMID 31801938, 2019). "In gastric cancer, miR-216a restrained tumor cells migration and invasion possibly by targeting JAK2/STAT3-mediated epithelial-mesenchymal transition (EMT)." (PMID 31798627, 2019).
gastric cancer (continued). "It was recently found that OSM promotes the proliferation, migration, and invasion of gastric cancer cells and that OSM and OSM receptor contribute to GC progression by activating STAT3/FAK/SRC signaling." (PMID 31871447, 2019). "In conclusion, we herein demonstrate that the putative STAT3 target, SPG20, is epigenetically silenced by promoter methylation in gastric cancer." (PMID 31194837, 2019). "In the current study, by methylation microarray, we identified that a potential STAT3 target, SPG20, is differentially methylated in gastric cancer." (PMID 31194837, 2019). "And the constitutive activation of STAT3 and CCND1 overexpression is accounted for the proliferation, migration and invasion in gastric cancer cells." (PMID 30143675, 2018). "Our analysis, thus, showed that abnormal expression of BMP1, COL1A1, STAT3, GATA6, SOX2 and FOXA2 forms an ubiquitous molecular signature of gastric cancer patients in Southwestern Taiwan." (PMID 29720137, 2018). "Our data suggest that ATO inhibits STAT3 activity and EMT process by upregulation of SHP-1 in gastric cancer cells." (PMID 29409467, 2018). "Taken together, our data suggest that pantoprazole modulate expression of p-JAK2/p-STAT3 (downregulation) and SHP-1 (upregulation) and EMT markers in gastric cancer cells." (PMID 30202514, 2018). "Taken together, our results suggest that pantoprazole downregulates JAK2/STAT3 signaling through inducing SHP-1 expression to modulate snail/E-cadherin expression and inhibit cellular migration or invasion in gastric cancer cells." (PMID 30202514, 2018). "Thus, STAT3 inhibitors may be effective only in patients with p-STAT3-positive gastric cancer." (PMID 29849601, 2018). "RECK has been shown to control metastases by signal transducer and activator of transcription 3 (STAT3)-dependent neoangiogenic switch; and to reduce the tumorigenesis of gastric cancer by inhibiting ADAM-mediated Notch1 shedding and activation." (PMID 29393911, 2018). "Among these genes, deregulation of STAT3, GATA6, SOX2, and FOXA2 in gastric cancer was already reported previously in independent studies." (PMID 29720137, 2018). "Because protein or gene expression level of SHP-1 is very weak in most of stomach cancer tissues, SHP-1-induction strategy appears to be reasonable to effectively inhibit constitutive STAT3." (PMID 30202514, 2018). "We have previously investigated promoter hypermethylation and gene expression of SHP-1 in most of gastric cancer cells and functional effects of SHP-1 on JAK2/STAT3 pathway." (PMID 30202514, 2018). "This suggests that B7-H3 silencing suppressed gastric cancer cell migration and invasion by reducing AKT, ERK, and Jak2/Stat3 pathway activation." (PMID 29069741, 2017). "Collectively these results suggested that the p-STAT3 and Bcl-2 was involved in the execution of apoptotic cell death in CA10 treated SGC-7901 gastric cancer cells." (PMID 29254150, 2017). "Another study by Zhu and colleagues has demonstrated the interaction between gastric cancer-derived mesenchymal stem cells (GC-MSCs) and neutrophils via the IL6/STAT3 axis." (PMID 28687755, 2017). "Active MSCs induce phosphorylation of NF-κB, ERK and STAT3, and inhibition of NF-κB activation by PDTC blocked the effects of activated MSCs on gastric cancer cells." (PMID 28350359, 2017). "To further substantiate the correlation between SIRT1 expression and survival outcome of patients with gastric cancer, we divided the patients into high and low SIRT1 and STAT3 expression groups." (PMID 28061480, 2017). "Western blot was performed to detect the protein levels of STAT3, phosphorylated-STAT3 (p-STAT3), Akt, phosphorylated-Akt (p-Akt) and CCK-BR in gastric cancer cells." (PMID 27518872, 2016).
gastric cancer (continued). "Our results demonstrate that there is an inverse relationship between the expression of STAT3 and GATA6 in gastric cancer patients." (PMID 27598141, 2016). "SALL4 knockdown greatly inhibited the expression of phosphorylated ERK, STAT3 and NF-κB, suggesting an important role of SALL4 in modulating the activation of these pathways in gastric cancer cells." (PMID 27819668, 2016). "In summary, our data demonstrate that CMTM3 suppresses gastric cancer metastasis via the STAT3/Twist1/EMT pathway, which will be helpful in our understanding of the pathogenesis of gastric cancer and provide novel clues for the early diagnosis of metastasis." (PMID 27121055, 2016). "Taken together, aberrant JAK/STAT3 signaling epigenetically silences a potential tumor suppressor, NR4A3, in gastric cancer, plausibly representing a reliable biomarker for gastric cancer prognosis." (PMID 27528092, 2016). "In a somewhat indirect mechanism in gastric cancer cells, LMP2A-activated STAT3 was found to increase DNMT1 levels which led to transcriptional repression of PTEN, a well-known tumor suppressor." (PMID 27458446, 2016). "Results from RNA sequencing identified an inverse correlation between the expression of STAT3 and GATA6 in 23 pairs of gastric cancer patient samples." (PMID 27598141, 2016). "We found that knockdown of CMTM3 promoted cell migration, invasion and tumor metastasis via the STAT3/Twist1/EMT pathway, which will be helpful to understand the pathogenesis of gastric cancer." (PMID 27121055, 2016). "In the current study, we first determined the expression of ASS1 in humanand murine gastric cancer cell lines and found that these cells displayed highprotein levels of both ASS1 and STAT3." (PMID 25928182, 2015). "To explore the signaling mechanisms of trastuzumab resistance in gastric cancer, we examined the phosphorylation status of Akt, ERK, and STAT3, which are well known to be major cell survival pathways mediated by Her2." (PMID 25669984, 2015). "It has been reported that in gastric cancer cells, IL-6 enhanced REG Iα transcription through the STAT3 activation." (PMID 25767811, 2015). "In conclusion, our results reveal that TGR5 is a suppressor of gastric cancer cell proliferation and migration and TGR5 activation suppresses STAT3 signaling pathway, indicating that TGR5 ligands have utility in anti-gastric cancer." (PMID 26417930, 2015). "Ponicidin has significant anti-proliferation effects by inducing apoptosis on gastric carcinoma cells in vitro, and induced apoptosis of MKN28 cells via the pathway regulated by JAK2 and STAT3 signaling pathways." (PMID 25588213, 2015). "STAT3 expression strongly correlated with VEGF expression and microvessel density in human gastric cancer." (PMID 25594045, 2014). "Consistent with our results, it has been found that the 17-AAG not only destabilizes the HIF-1α protein in prostate cancer cells but also disrupts STAT3- HIF-1α activation axis in pancreatic and gastric cancer cells." (PMID 24658058, 2014). "This novel combination strategy warrants further clinical investigation in patients with trastuzumab-resistant tumors given that constitutively activated STAT3 is present in a quite fraction of patients with HER2-positive breast and gastric cancer." (PMID 25327561, 2014). "We confirmed the up-regulation of p-STAT3, p-ERK and p-NF-κB protein levels by the supernatants from the activated MSCs in another gastric cancer cell line SGC7901." (PMID 24824968, 2014). "Previously, it has been shown that AG490 markedly inhibits angiotensin II-induced STAT3 activation and the expression of MMP-2 and VEGF in gastric cancer cells." (PMID 24520293, 2014). "In gastric cancer cells with MET amplification, the MET-TKIs markedly inhibited AKT, ERK, and STAT3 signaling and triggered apoptosis, whereas such effects were not evident in cells without MET amplification." (PMID 23327903, 2013).
gastric cancer (continued). "Correlation between STAT3, survivin, IL-6, VEGF expression and TNM stages in gastric cancer patients." (PMID 24116074, 2013). "Survival of patients with gastric cancer was lower with AFP and STAT3 double overexpression than with overexpression of either alone." (PMID 23382965, 2013). "As expected, a single band was observed using each antibody, and the protein levels of IL-6, survivin, STAT3, p-STAT3 and VEGF in human gastric cancer tissues were all significantly higher than those in adjacent normal mucosa tissues (all P<0.001)." (PMID 24116074, 2013). "Previous study has shown that phosphorylation of STAT-3 and VEGF protein expression are increased in human gastric cancer tissue, which in turn elevate the angiogenic phenotype and contribute to gastric cancer development and progression." (PMID 22937084, 2012). "In KRAS mutant gastric cancer cells, either p-ERK or p-STAT3 was also increased upon treatment of NVP-BKM120." (PMID 22159814, 2012). "In diverse cancers including gastric cancer, the STAT pathway, especially STAT3, is constitutively activated and plays a major role in tumorigenesis." (PMID 22159814, 2012). "Accordingly, Stat3 is required for endothelial cell survival and their arrangement into new vascular structures, while nuclear Stat3 correlates with enhanced VEGF expression and microvessel density in gastric cancer." (PMID 20478049, 2010). "This experiment provides in vitro evidence to confirm that STAT3 and c-Jun, under catecholamine stimulation, can physically interact and bind to the AP-1 site to achieve transactivation of MMP-7 gene in gastric cancer cells." (PMID 20939893, 2010). "Additionally, the natural polyphenol epigallocatechin gallate (EGCG) exerts dual immunomodulatory effects by transcriptionally repressing STAT3, thereby downregulating PLXNC1 expression and reducing exosomal miR-92b-5p levels in gastric cancer cells." (PMID 41229433, 2025). "Similarly, the upregulation of miR-135b-5p in gastric cancer promotes tumor invasiveness by targeting CLIP4, thereby impairing the tumor-suppressive JAK2/STAT3 signaling pathway." (PMID 41229433, 2025). "Moreover, PTL has been reported to enhance the sensitivity of gastric cancer cells to cisplatin (DDP) and to reverse drug resistance by inhibiting the STAT3 signaling pathway." (PMID 40051564, 2025). "Furthermore, studies have demonstrated that in aggressive tumors such as bladder and gastric cancers, EDNRA expression is influenced by the upregulation of the STAT3 signaling pathway." (PMID 41515956, 2025). "This research focused on the molecular processes involved in the STAT3/FAK pathways, which may indicate suppression at the early stages of gastric cancer development." (PMID 40217305, 2025). "Additionally, gastric cancer cell-derived extracellular vesicles (GC-EVs) have been shown to transport high-mobility group box-1 (HMGB1), which activates STAT3 and upregulates PD-L1 expression in neutrophils." (PMID 40387965, 2025). "miR-BART5-5p overexpression in EBV negative gastric cancer cells caused a reduction of PIAS3 and then STAT3 stimulation followed by PD-L1 upregulation." (PMID 40855561, 2025). "Furthermore, in gastric cancer, the combination treatment's impact on inhibiting the JAK/STAT3 pathway was greater compared to the use of separate treatments." (PMID 40350446, 2025). "Similarly, after treatment with 47 μM calycosin in gastric cancer cell AGS, cancer cell apoptosis is promoted by the increased ROS level and activated MAPK/STAT3/NF-κB pathway, resulting in G0/G1 cell cycle arrest and lower cell proliferation." (PMID 41463300, 2025). "Additionally, macrophages serve as major sources of CXCL1 and CXCL5 in the gastric cancer microenvironment, and promote the migration of gastric cancer cells by activating a CXCR2/STAT3 feed-forward loop." (PMID 41583453, 2025).